RNU6-914P (RNA, U6 small nuclear 914, pseudogene)
Gene: Small nuclear RNA gene on chromosome 8 (98,192,205 to 98,192,313, reverse strand). Ensembl gene ENSG00000252558.
Homologues: Orthologues: chimpanzee U6 (99% identical), macaque U6 (87% identical). Paralogues in human: RNU6-774P (76% identical), RNU6-468P (74% identical), RNU6-66P (74% identical), RNU6-1011P (73% identical), RNU6-11P (73% identical), RNU6-1331P (73% identical), RNU6-189P (73% identical), RNU6-218P (73% identical), RNU6-21P (73% identical), RNU6-23P (73% identical), RNU6-37P (73% identical), RNU6-744P (73% identical), and 1284 more.